TYW2 (tRNA wybutosine-synthesizing protein 2)
Description:
S-adenosyl-L-methionine-dependent transferase that acts as a component of the wybutosine biosynthesis pathway. Wybutosine is a hyper modified guanosine with a tricyclic base found at the 3'-position adjacent to the anticodon of eukaryotic phenylalanine tRNA. Catalyzes the transfer of the alpha-amino-alpha-carboxypropyl (acp) group from S-adenosyl-L-methionine to the C-7 position of 4-demethylwyosine (imG-14) to produce wybutosine-86.
Synonyms: TRM12; TRMT12; FLJ20772
Tractability: PROTAC: ubiquitination databases record sites on it.
Gene: Protein-coding gene on chromosome 8 (124,450,820 to 124,462,150, forward strand). Ensembl gene ENSG00000183665.
Subcellular location (Human Protein Atlas): Nucleoplasm; Mitochondria
Pathways (Reactome):
Metabolism of RNA: Synthesis of wybutosine at G37 of tRNA(Phe)
Gene Ontology:
Molecular function: protein binding; tRNA 4-demethylwyosine alpha-amino-alpha-carboxypropyltransferase activity
Biological process: wybutosine biosynthetic process; tRNA modification
Cellular component: cytoplasm
Genetic constraint (gnomAD): Loss-of-function variants: 2 observed, 7.53 expected, observed/expected ratio (o/e) 0.27, 90% interval 0.11 to 0.84. That is too few expected variants to judge how well the gene tolerates losing a copy. Missense variants: 487 observed, 581.03 expected, observed/expected ratio (o/e) 0.84, 90% interval 0.78 to 0.9. Synonymous variants: 196 observed, 226.22 expected, observed/expected ratio (o/e) 0.87, 90% interval 0.77 to 0.98.
Homologues: Orthologues: macaque TRMT12 (96% identical), guinea pig TRMT12 (82% identical), rat Trmt12 (80% identical), mouse Trmt12 (79% identical), rabbit TRMT12 (73% identical), tropical clawed frog trmt12 (52% identical), zebrafish trmt12 (46% identical), Caenorhabditis elegans F40F9.10 (26% identical). Paralogues in human: TRMT5 (17% identical), TYW3 (8% identical).
Diseases named in the same sentence as TYW2 in open-access papers:
TYW2 is named in the same sentence as 9 diseases in open-access papers, as found by Europe PMC text mining. Sharing a sentence is not in itself a finding about the gene and the disease. The quoted sentences say what the papers report.
colorectal cancer (3 papers, 2020 to 2026). A primary or metastatic malignant neoplasm that affects the colon or rectum. "Even more important from the clinical side, the DNA methylation-linked loss of TYW2 was associated with poor clinical outcome in colorectal cancer patients at early stages of the disease." (PMID 32778592, 2020). "For the entire population of colorectal cancer patients, low TYW2 expression levels showed a trend toward its association with poor overall survival, but this was not statistically significant (P = 0.320, log-rank test)." (PMID 32778592, 2020). "To do so, we data-mined the colorectal carcinoma cases from the TCGA effort in which we had previously identified the presence of TYW2 hypermethylation and associated silencing for the 371 available tumors with complete clinical information." (PMID 32778592, 2020). "Thus, the higher frequency of aberrant TYW2 DNA methylation-associated transcriptional silencing observed in colorectal cancer prompted us to focus our efforts on this tumor type." (PMID 32778592, 2020). "Most importantly, the epigenetic defect in TYW2 was associated with poor clinical outcome of the studied colorectal cancer, an observation that can be linked to the acquisition of enhanced cellular migration features and epithelial-to-mesenchymal features on TYW2 loss." (PMID 32778592, 2020). "After detecting the presence of TYW2 CpG island hypermethylation-associated transcriptional loss in colorectal cancer cell lines, we studied its contribution to the chemical modification status of G37 using tRNA-associated liquid chromatography-mass spectrometry (LC/MS)." (PMID 32778592, 2020). "Importantly, TYW2 silencing in cancer cells confers enhanced migration and epithelial-to-mesenchymal features that are associated in early-stage colorectal cancer patients with poor clinical outcome." (PMID 32778592, 2020). "In this regard, colorectal cancer cell lines were the most frequently TYW2-hypermethylated tumor type, and TYW2 hypermethylation was also associated with transcript down-regulation, mimicking the results observed in the TCGA cohorts." (PMID 32778592, 2020). "We first assessed the profile of the modified nucleosides of G37 according to the TYW2 CpG island methylation status in the studied colorectal cancer cell lines." (PMID 32778592, 2020). "In contrast, the TYW2 promoter CpG island was methylated in 19.03% (79 of 415) of the primary colorectal carcinomas available in the TCGA." (PMID 32778592, 2020). "However, when subdivided by stage, early-stage colorectal cancer patients with TYW2 low expression levels showed significantly reduced overall survival (HR = 4.78; 95% CI = 2.03 to 11.27; P < 0.001, log-rank test)." (PMID 32778592, 2020). "However, when subdivided by stages, colorectal cancer patients with early-stage disease (n = 184, stage I and II) harboring TYW2 epigenetic inactivation showed significantly reduced overall survival (hazard ratio [HR] = 2.984; 95% confidence interval [CI] = 1.26 to 7.08; P = 0.009, log-rank test)." (PMID 32778592, 2020).
breast carcinoma (2 papers, 2012 to 2018). "Our previous report on the amplification and overexpression of this gene in breast cancer is the only report on mammalian TYW2." (PMID 22761755, 2012). "Previously, we demonstrated that human TYW2 (hTYW2) was amplified and overexpressed in breast cancer." (PMID 22761755, 2012). "Eight individual tumor samples were obtained from three different types of transgenic mouse mammary tumor models, and tested for Tyw2 expression." (PMID 22761755, 2012). "We previously reported that the human TYW2 is overexpressed in breast cancer." (PMID 22761755, 2012). "In this study, we identify a mouse mammary tumor model that overexpresses Tyw2 and explore whether the biosynthesis of yW base is compromised in tRNAPhe from the tumors." (PMID 22761755, 2012).
colon cancer (1 paper, 2020). "Using a Transwell assay, we found that CRISPR/cas9-mediated deletion of TYW2 in the unmethylated and expressing HCT-116 and SW480 colon cancer cell lines induced a significant increase in the migration potential of the obtained TYW2-deficient cells." (PMID 32778592, 2020). "Most importantly, we wondered whether this type of cellular reprogramming was occurring on TYW2 loss in epithelial tumors such as colon cancer, in which the migration, cellular detachment, and invasion capacities involve the EMT." (PMID 32778592, 2020). "Thus, the 109 transcripts identified constitute bona fide candidates for direct targeting by TYW2 epigenetic loss in the colon cancer cells." (PMID 32778592, 2020). "We analyzed in more detail the link between TYW2 promoter CpG island hypermethylation and transcriptional inactivation of the gene at the RNA and protein levels in colon cancer cell lines." (PMID 32778592, 2020). "Thus, losing TYW2 and hypermodified yW in colon cancer cells confers a phenotype prone to ribosomal frameshifting events." (PMID 32778592, 2020). "The physiological status quo for mRNA levels is distorted in human tumors, and we wondered whether TYW2 epigenetic loss by generation of hypomodified guanosine and −1 PRF could induce aberrant mRNA degradation in colon cancer." (PMID 32778592, 2020). "Importantly, the TYW2 hypermethylated colon cancer cell lines SW48 and HT-29 minimally expressed the TYW2 RNA transcript and protein, as determined by quantitative real-time PCR and Western blot analysis, respectively." (PMID 32778592, 2020). "In this regard, we found that TYW2 CRISPR/Cas9-mediated deletion in both HCT-116 and SW480 colon cancer cells induced down-regulation of E-cadherin and up-regulation of vimentin." (PMID 32778592, 2020).
colorectal tumors (1 paper, 2020). "Data mining of the TCGA RNA-sequencing (RNA-seq) data available in colorectal tumors showed that TYW2 hypermethylation was associated with transcript down-regulation (Spearman rho = −0.47; P < 0.0001)." (PMID 32778592, 2020). "Promoter CpG island hypermethylation-associated silencing of TYW2 was observed across a wide spectrum of human cancer types, with colorectal tumors the most common type of tumor in which this epigenetic defect was identified." (PMID 32778592, 2020). "Here we report that the tRNA-yW Synthesizing Protein 2 (TYW2) undergoes promoter hypermethylation-associated transcriptional silencing in human cancer, particularly in colorectal tumors." (PMID 32778592, 2020). "For the entire population of colorectal tumors, TYW2 promoter hypermethylation showed a trend toward an association with poor overall survival, but this was not statistically significant (P = 0.460, log-rank test)." (PMID 32778592, 2020). "Beyond colorectal tumors, the TYW2 promoter CpG island was also commonly hypermethylated in cervical (17.37%; 45 of 259), gastric (12.88%; 51 of 396)." (PMID 32778592, 2020).
cancer (5 papers, 2015 to 2026). A tumor composed of atypical neoplastic, often pleomorphic cells that invade other tissues. "While yW and its derivatives are biosynthesized by five enzymes, known as tRNA-yW Synthesizing Proteins 1-5 (TYW1-5), epigenetic silencing of TYW2 was found to be the leading cause for yW deficiency in cancer." (PMID 41190243, 2025). "The epigenetic loss of TYW2 induces guanosine hypomodification in phenylalanine-tRNA, an increase in −1 ribosome frameshift events, and down-regulation of transcripts by mRNA decay, such as of the key cancer gene ROBO1." (PMID 32778592, 2020). "Thus, the loss of the multifaceted cancer gene ROBO1 on TYW2 epigenetic inactivation provides an illustrative example of how alterations of tRNA chemical modifications might contribute to tumorigenesis." (PMID 32778592, 2020). "Here we demonstrate that the generation of hypomodified G37 in tRNAPhe is due to the cancer-specific epigenetic inactivation of the tRNA- modifying enzyme TYW2." (PMID 32778592, 2020). "Thus, TYW2 loss is associated with increased migration capacity and the emergence of EMT features, both of which have central roles in metastasis development, the leading cause of cancer-associated mortality." (PMID 32778592, 2020). "TRMT12 (also known as TYW2) is a tRNA modification enzyme that affects codon-specific translation by modulating the G37 site of tRNA, thereby regulating the occurrence and development of cancer." (PMID 41501031, 2026).
tumor (3 papers, 2012 to 2026). "The transcriptomic assay showed that numerous RNAs were targeted by this tumor-specific event induced on TYW2 silencing." (PMID 32778592, 2020). "We found that TYW2 undergoes tumor-specific silencing by promoter CpG island hypermethylation, preventing formation of the hypermodified forms of G37." (PMID 32778592, 2020).
TYW2 also shares sentences with these, for which no sentence is quoted: head and neck squamous cell carcinoma (1 paper); neurological disorders (1); oral squamous cell carcinoma (1).